SLC34A2 (solute carrier family 34 member 2)
Diseases named in the same sentence as SLC34A2 in open-access papers (continued):
Sharing a sentence is not in itself a finding about the gene and the disease.
gastric cancer (8 papers, 2018 to 2021). A primary or metastatic malignant neoplasm involving the stomach. "In gastric cancer, knockdown of miR-939 modulated metastasis and chemoresistance via dysregulation of SLC34A2 and Raf/MEK/ERK pathway." (PMID 32908582, 2020). "SLC34A2 was shown to be regulated by miR-939 in gastric cancer cell lines and tissues and miR-939 was associated with CDR in gastric cancer patients." (PMID 35582590, 2019). "In 5-fluorouracil-resistant gastric cancer, miR-939 is downregulated and results in increased expression level of SLC34A2." (PMID 29967761, 2018). "Previous study has shown that SLC34A2 could target the MIR25 promoter to promote gastric cancer progression 19; we wondered whether the SLC34A2–miR‐25 axis exists in neuroblastoma cells." (PMID 30868061, 2019). "Recently, it was shown that miR-939 targets direct SLC34A2 in gastric cancer." (PMID 29967761, 2018). "In gastric cancer (GC), by targeting SLC34A2, the overexpression of miR-939 in GC cells significantly decreased Raf-1, p-MEK1/2 and p-ERK expression levels for suppressing the chemoresistance and metastasis of GC34." (PMID 29403024, 2018). "In in vitro models of gastric cancer, overexpression of miR-939 strongly decreased MEK1/2 phosphorylation as well as Raf-1 level, whereas SLC34A2 restoration rescued these effects." (PMID 29967761, 2018). "Tumor suppressor miR-195-5p, miR-204, miR-623, miR-939 and miR-124 have been shown to be involved in overcoming 5-FU resistance of gastric cancer via silencing Zing finger 139 (ZNF139), TGFBR2, cyclin D1 (CCND1), solute carrier family 34 member 2 (SLC34A2) and EZH2, respectively." (PMID 32192494, 2020). "Mechanistically, we found that SLC34A2 could directly bind to the promoter of MIR25 and thus upregulate its level, which is consistent with the previous study showing that SLC34A could regulate miR‐25 activity to affect gastric cancer progression." (PMID 30868061, 2019).
thyroid cancer (7 papers, 2015 to 2023). "SLC34A2 was an oncogene highly expressed in a variety of tumors, including lung, ovarian, colorectal, and thyroid cancer, and was associated with tumor metastasis and recurrence of colorectal and thyroid cancer." (PMID 33613767, 2021). "Among the BRAFV600E-specific differentially expressed 18 genes, there are two involved in the calcification of epithelial cells: SLC34A2 and ITPR3, with the latter not previously related to BRAF mutation or to thyroid cancer." (PMID 26625260, 2015).
colorectal cancer (6 papers, 2015 to 2025). A primary or metastatic malignant neoplasm that affects the colon or rectum. "Survival of patients with colorectal cancer is also reduced, and colorectal cancer cell proliferation is promoted by high levels of SLC34A2." (PMID 40643473, 2025). "Significantly, SLC34A2-induced EZH2 overexpression promoted the proliferation and chemo-resistance to apoptosis in colorectal cancer (CRC) cells in vitro and in vivo." (PMID 30038060, 2019).
ovarian tumors (6 papers, 2017 to 2024). "SLC34A2 mutations in breast and thymic tumors reduce the life expectancy of patients, and SLC34A2 overexpression was found to reduce the life expectancy of patients with brain tumors, ovarian tumors, and pancreatic tumors." (PMID 37035196, 2023). "We confirmed the published data that SLC34A2 is upregulated in ovarian tumors compared to relatively healthy ovarian tissues." (PMID 34944522, 2021). "To compare the expression levels of the SLC34A2 gene, coding for NaPi2b, among the different classifications of the ovarian tumors (OT), we subdivided the samples into groups based on histology, grade and stage." (PMID 28464843, 2017). "Interestingly, when a clinical upifitamab scFv against a type-2 sodium-dependent phosphate transporter named SLC34A2 (NaPi2b), known to be highly elevated in ovarian tumors was tested, almost undetectable surface expression of NaPi2b on HeyA8 cells was observed as compared to OVCAR3." (PMID 37838774, 2023).
papillary thyroid carcinoma (6 papers, 2014 to 2023). "Previous studies highlighted the involvement of DNA methylation in the regulation of the SLC44A4 and SLC34A2 in colon adenocarcinoma, renal cell carcinoma, small-cell lung cancer, and papillary thyroid carcinoma." (PMID 37397501, 2023).
lung adenocarcinoma (5 papers, 2014 to 2024). A carcinoma that arises from the lung and is characterized by the presence of malignant glandular epithelial cells. "High SLC34A2 expression was present in approximately 75% of lung adenocarcinoma samples and was associated with significantly improved overall patient survival." (PMID 37035196, 2023). "It was also suggested that the lack of Pi might aid the escape of abnormal AT II cells from complement-associated immunosurveillance in the initial stages of lung adenocarcinoma development, when downregulation of SLC34A2 induces aberrant Pi transport." (PMID 25017204, 2014). "This suggested that SLC34A2 might be associated with the initiation and progression of lung adenocarcinoma." (PMID 25017204, 2014). "Therefore, downregulation of SLC34A2 might cause abnormal AT II cells to develop into lung adenocarcinoma cells." (PMID 25017204, 2014). "Downregulation of SLC34A2 may primarily cause abnormal AT II cells to escape from complement-associated immunosurveillance and abnormally express certain tumor-suppressor genes inducing AT II cells to develop into lung adenocarcinoma." (PMID 25017204, 2014). "Among them, low expression of C12orf56, DLX5, DSC3, FEZF1, GSTA1, H2BC9, IGSF11 and high expression of EREG, CEACAM6, SLC34A2 in lung adenocarcinoma were found to predict poor prognosis for patients." (PMID 37035196, 2023). "For further examining the potential mechanisms of SLC34A2 in lung adenocarcinoma, differentially expressed genes between A549-P and A549-P-S cells were screened using microarray analysis." (PMID 25017204, 2014). "In order to investigate the effects of SLC34A2 upregulation in human lung adenocarcinoma, A549 cells stably expressing SLC34A2 (A549-P-S) or PcDNA3.1 vector (A549-P) were initially selected by G418." (PMID 25017204, 2014). "Foremost, our recent research found that expression of SLC34A2 was down-regulated in lung adenocarcinoma cell line A549 and elevated expression of SLC34A2 could significantly inhibit cell viability and invasion of A549 in vitro." (PMID 26156586, 2015). "The present study first determined that the expression levels of SLC34A2 were downregulated in A549 and H1299 lung adenocarcinoma cells, then further revealed that the elevated expression of SLC34A2 was able to significantly inhibit the viability and invasion of A549 cells in vitro." (PMID 25017204, 2014). "Therefore, our data suggested that a low Pi environment induced by downregulation of SLC34A2 in A549 cells may cause expression changes of these genes associated with tumorigenesis signaling pathways, resulting in AT II cells that develop into lung adenocarcinoma cells." (PMID 25017204, 2014). "Thus, it was hypothesized that a lower expression of SLC34A2 in AT II cells might lead to the deficiency in Pi, which might cause the hyperproliferation and lack of differentiation of AT II cells, and then cause these abnormal AT II cells to transform into lung adenocarcinoma." (PMID 25017204, 2014). "qPCR was performed to investigate whether the expression of SLC34A2 was different in A549 and H1299 lung adenocarcinoma cells compared with normal human bronchial HBE cells." (PMID 25017204, 2014). "Abnormal expression of solute carrier family 34 (sodium phosphate), member 2 (SLC34A2) in the lung may induce abnormal alveolar type II (AT II) cells to transform into lung adenocarcinoma cells, and may also be important in biological process of lung adenocarcinoma." (PMID 25017204, 2014). "SLC34A2 might therefore be important in the development of lung adenocarcinoma." (PMID 25017204, 2014).
lung disease (5 papers, 2020 to 2025). "In humans, this pulmonary disorder is a rare autosomal recessive disorder triggered by a mutation in the gene SLC34A2, which causes deposition and aggregation of calcium and phosphate in the pulmonary parenchyma with formation of microliths." (PMID 33028333, 2020). "Since mutations in SLC34A2 which reduce phosphate transport are linked to lung disease, we speculate that any SNPs which alter SLC34A2 activity might indirectly affect F508del-CFTR function and potentially impact the outcome of CFTR corrector therapies." (PMID 34020896, 2021).
bladder cancer (4 papers, 2017 to 2025). "Highly expressed levels of SLC34A2 in bladder cancer are associated with increased tumor size and lower patient survival, and depletion of SLC34A2 inhibits bladder tumor growth in vivo." (PMID 40643473, 2025). "In this study, we investigate the clinical significance of SLC34A2 and its function in human bladder cancer (BC)." (PMID 28151475, 2017). "For instance, we found that SLC34A2 was downregulated in COAD and BLCA, while previous studies reported that this transporter was upregulated in tumor tissues of colorectal and bladder cancer patients." (PMID 37397501, 2023). "Similarly, SLC34A2 expression has been reported as an independent factor for shorter DFS in CRC and bladder cancer." (PMID 34336552, 2021).
glioma (4 papers, 2019 to 2022). A benign or malignant brain and spinal cord tumor that arises from glial cells (astrocytes, oligodendrocytes, ependymal cells). "In glioma cells, SLC22A18, SLC8A2, SLC9A1, and SLC34A2 were examined as the risk genes of glioma." (PMID 32565801, 2020). "Concerning brain cancer, it has been shown previously that SLC34A2 is overexpressed in glioma, but the relation of increased expression with the life expectancy of patients has not been studied." (PMID 34944522, 2021). "SLC34A2 (solute carrier family 34 member A2) is a member of the SLC34 family and is usually overexpressed in glioma tissues and cell lines." (PMID 35280808, 2022).
brain tumors (3 papers, 2021 to 2025). "Levels of SLC34A2 in “well-differentiated endometrioid” carcinomas are overexpressed, and patients with tumors of the brain, pancreas, and ovaries have reduced lifespans associated with SLC34A2 overexpression." (PMID 40643473, 2025). "The analysis of the SLC34A2 expression data showed the potential impact of SLC34A2 upregulation being related to poor survival prognosis in ovarian, pancreatic, and brain tumors." (PMID 34944522, 2021).
glioblastoma (3 papers, 2013 to 2022). The most malignant astrocytic tumor (WHO grade IV). "Unlike TRK-A, activation of ROS1 typically occurs when it is fused to oncogenic fusion partners such as fused in glioblastoma and solute carrier family 34 member 2 (SLC34A2)." (PMID 24386191, 2013). "In addition, many partners, such as solute carrier family 34 member 2 (SLC34A2), cluster of differentiation 74 (CD74), fused in glioblastoma, Syndecan 4 (SDC4) and Ezrin (EZR), are rearranged with ROS1 in NSCLC." (PMID 35628598, 2022).
colitis (2 papers, 2017 to 2024). Inflammation of the colon. "Impact of HFD on DSS‐induced colitis may be linked to intestinal dysbiosis and specific genes such as Abca8b, Ace2, Apoa1, Apoa4, Apoc3, Aspa, Dpp4, Maob, Slc34a2, Slc7a9, and Trpm6." (PMID 39479684, 2024). "Overall, the findings indicate that the impact of HFD on DSS‐induced colitis may be linked to intestinal dysbiosis and specific genes such as Abca8b, Ace2, Apoa1, Apoa4, Apoc3, Aspa, Dpp4, Maob, Slc34a2, Slc7a9, and Trpm6." (PMID 39479684, 2024).
endometrial cancer (2 papers, 2021 to 2025). Primary or metastatic malignant neoplasm involving the endometrium (mucous membrane that lines the endometrial cavity). "Upregulation in myeloid and bowel tumors was found in several studies; the overexpression of SLC34A2 was found in endometrioid and papillary serous ovarian carcinomas, and it was shown that in uterine (endometrial) cancer, SLC34A2 expression appeared relatively increased." (PMID 34944522, 2021).
endometrioid ovarian carcinomas (2 papers, 2017 to 2021). "Interestingly, we have shown previously that SLC34A2 is overexpressed in well-differentiated papillary serous and endometrioid ovarian carcinomas which usually have a good prognosis." (PMID 34944522, 2021).
neuroblastoma (2 papers, 2019 to 2023). Neuroblastoma (NB) is the most common solid, extracranial childhood tumor. "doi: 10.1002/2211-5463.12620 2 Chen J, Wang P, Cai R, Peng H, Zhang C and Zhang M SLC34A2 promotes neuroblastoma cell stemness via enhancement of miR-25/Gsk3β-mediated activation of Wnt/β-catenin signaling." (PMID 37219054, 2023). "We found that SLC34A2 expression was negatively correlated with the overall survival and relapse‐free survival probability of neuroblastoma patients." (PMID 30868061, 2019). "Our results demonstrate that miR‐25/Gsk3β‐mediated activation of Wnt signaling is responsible for SLC34A2‐induced enhancement of neuroblastoma cell stemness." (PMID 30868061, 2019). "Bioinformatics analysis showed that miR‐25 is a potential target of SLC34A2 and SLC34A2 expression was negatively correlated with the survival rate of neuroblastoma patients." (PMID 30868061, 2019). "Knockdown of SLC34A2 attenuated the expression of stemness markers and spheroid formation capacity of neuroblastoma cell‐derived spheroids, and overexpression of SLC34A2 exerted the opposite effects in neuroblastoma cells." (PMID 30868061, 2019). "Transfection of miR‐25 inhibitor or a Gsk3β overexpression plasmid attenuated the effects of SLC34A2 overexpression on the stemness of neuroblastoma cells." (PMID 30868061, 2019). "SLC34A2 expression was negatively correlated with the overall survival and relapse‐free survival of neuroblastoma patients." (PMID 30868061, 2019). "Here, we examined the roles of the transcription factor SLC34A2 in regulating the stemness of neuroblastoma cells." (PMID 30868061, 2019). "As expected, we revealed that SLC34A2 positively regulated the stemness of neuroblastoma cells through a spheroid formation assay." (PMID 30868061, 2019). "Since CSCs contribute to tumor progression, here we focused on the role of SLC34A2 in regulating the stemness of neuroblastoma cells." (PMID 30868061, 2019). "We firstly evaluated the correlation between SLC34A2 expression and the survival of neuroblastoma patients." (PMID 30868061, 2019). "Finally, we demonstrated that SLC34A2‐mediated effects on the stemness of neuroblastoma cells were at least through the miR‐25–Gsk3β axis, establishing the SLC34A2–miR‐25–Gsk3β regulatory axis in neuroblastoma cells." (PMID 30868061, 2019). "Importantly, SLC34A2 expression is negatively correlated with the overall survival of neuroblastoma patients." (PMID 30868061, 2019). "Since CSCs contribute to tumor progression, we explored whether SLC34A2 regulates the stemness of neuroblastoma cells." (PMID 30868061, 2019). "Additionally, SLC34A2 expression was observed to be remarkably increased in spheroids derived from neuroblastoma cells." (PMID 30868061, 2019). "This work provides evidence confirming that SLC34A2 could be a novel candidate for neuroblastoma treatment or prognosis." (PMID 30868061, 2019). "Notably, SLC34A2 expression was remarkably decreased in neuroblastoma cell spheroids relative to parental cells, while miR‐25 exhibited an opposite effect." (PMID 30868061, 2019). "However, we cannot exclude that there are other pathways involved in SLC34A2‐mediated effects in neuroblastoma cell stemness." (PMID 30868061, 2019). "Our results demonstrate that SLC34A2 promotes the stemness of neuroblastoma cells." (PMID 30868061, 2019). "However, the roles of SLC34A2 in neuroblastoma progression are still unclear." (PMID 30868061, 2019). "In conclusion, our results indicate that SLC34A2 could directly bind to the promoter of MIR25 and thus facilitate miR‐25–Gsk3β axis‐mediated activation of Wnt signaling, which is responsible for the SLC34A2‐mediated effects on the stemness of neuroblastoma cells." (PMID 30868061, 2019). "However, we must admit that the conclusion should be validated by in vivo experiment, and future works could focus on the role of SLC34A2 in regulating other functions of neuroblastoma cells, such as cell migration and invasion." (PMID 30868061, 2019).
neuroblastoma (continued). "Thus, we assumed that SLC34A2 might promote the stemness of neuroblastoma cells through miR‐25/Gsk3β‐mediated activation of Wnt signaling." (PMID 30868061, 2019). "However, the roles of SLC34A2 in neuroblastoma progression remain unclear." (PMID 30868061, 2019). "Notably, we found that SLC34A2 expression was significantly increased in spheroids formed by SH‐SY5Y cells, which prompted us to explore the roles of SLC34A2 in the stemness of neuroblastoma cells." (PMID 30868061, 2019).
brain cancer (1 paper, 2021). A primary or metastatic malignant neoplasm affecting the brain. "The multivariate survival analysis demonstrated that the level of SLC34A2 expression is one of the key parameters for ovarian, pancreatic, and brain cancer patient survival." (PMID 34944522, 2021). "The multivariate analysis of the CNS and brain cancer dataset showed that the level of SLC34A2 mRNA expression has a hazard ratio of 2.07 (CI: 0.99–4.3); the parameter with a higher hazard ratio was only Neoplasm Disease Lymph Node Stage N3." (PMID 34944522, 2021).
Breast invasive carcinoma (1 paper, 2021). "The life expectancy of patients with mutations in the SLC34A2 gene is significantly lower than in patients without gene alterations in studies of breast (p < 0.042) and thymus (p < 0.0008) tumors (cBioPortal, TCGA: Breast invasive carcinoma, n = 1082, Thymoma, n = 122)." (PMID 34944522, 2021).
co-infection (1 paper, 2019). "Upon intratumor injection with cisplatin, the size of xenograft tumors in co-infection group with p-EZH2 and si-SLC34A2 abolished the reduction in xenograft tumors resulting from si-SLC34A2 infection alone." (PMID 30038060, 2019). "Cell viability of si-SLC34A2 cells was significantly reduced, while the co-infection with p-EZH2 and si-SLC34A2 reversed the cell viability." (PMID 30038060, 2019). "Similarly, co-infection group with p-EZH2 and si-SLC34A2 relieved the higher TUNEL index due to si-SLC34A2 infection alone." (PMID 30038060, 2019).
cystic fibrosis (1 paper, 2021). Autosomal recessive disorder caused by pathogenic variants in the CFTR gene (cystic fibrosis transmembrane conductance regulator), which encodes a chloride and bicarbonate channel expressed in epithelial cells, and follow the diagnosis criteria. "•Cystic fibrosis airway epithelia express the phosphate transporter SLC34A2." (PMID 34020896, 2021).
endometrioid tumor (1 paper, 2017). A benign, borderline, or malignant epithelial tumor of the female reproductive system characterized by the presence of glands and/or cysts lined by neoplastic cells that resemble endometrial cells. "The expression of SLC34A2 differed significantly among the histological groups with a less pronounced expression mainly in the mucinous tumors but also in the endometrioid tumors." (PMID 28464843, 2017).
herpesvirus infection (1 paper, 2025). "We demonstrate that herpesvirus infection induces the expression of the embryonic transcription factor DUX4, which subsequently activates its downstream target, SLC34A2, a phosphate transporter." (PMID 41211819, 2025).
lung squamous cell carcinoma (1 paper, 2023). "Ten prognostic beneficial factors of the heterogeneous expression of lung squamous cell carcinoma genes driven by TTN mutations were screened for and DLX5, FEZF1, H2BC9, EREG, and SLC34A2 were identified as the main factors of the prognostic models." (PMID 37035196, 2023).